PDGFRA (platelet derived growth factor receptor alpha)
Diseases named in the same sentence as PDGFRA in open-access papers (continued):
Sharing a sentence is not in itself a finding about the gene and the disease.
schwannoma (4 papers, 2012 to 2025). A benign, usually encapsulated slow growing tumor composed of Schwann cells. "Analysis of phospho-receptor tyrosine kinase and phospho-kinases proteome profiler arrays revealed that schwannomas consistently had higher levels of phosphorylated PDGFRα, PDGFRβ, SRC, MEK and STAT3 compared with control primary HSC." (PMID 28427224, 2017). "Schwannomas exhibited averaged 6.6 times higher PDGFRα phosphorylation, 5.4 times higher PDGFRβ phosphorylation, 30 times higher SRC phosphorylation, 5.6 times higher MEK phosphorylation and 7.4 times higher STAT3 phosphorylation compared with control primary HSC." (PMID 28427224, 2017). "Following merlin depletion, HSC increased the levels of phosphorylated SRC and PDGFRα/β, in agreement with studies in primary human NF2 schwannoma cells." (PMID 28427224, 2017). "To assess activation of PDGFRα/β and SRC in human schwannomas, we surveyed a phospho-proteome profile comparing five human vestibular schwannoma specimens with primary normal adult human Schwann cells cultured in the presence of mitogens to stimulate their proliferation." (PMID 28427224, 2017).
scleroderma (4 papers, 2012 to 2023). Scleroderma is a rare autoimmune connective tissue disorder characterized by abnormal hardening of the skin and, sometimes, other organs. "Triggering this intracellular loop by specific autoantibodies against PDGFRα might sustain the myofibroblast phenotype conversion and the persistent profibrotic response of SSc fibroblasts, suggesting a causal role in the pathogenesis of scleroderma." (PMID 35409263, 2022). "The absence of human fibroblasts in scleroderma skin grafts was corroborated by immunofluorescence imaging of scleroderma skin grafts before and after transplantation using human and mouse PDGFRA antibodies." (PMID 37669366, 2023). "We first studied, by immunohistochemistry, the expression of PDGFRα and PDGFRβ in scleroderma versus normal skin." (PMID 22697462, 2012). "Prior to skin transplantation, human fibroblasts were apparent in the scleroderma donor skin, whereas 4 wk posttransplantation, scleroderma skin grafts were largely devoid of human fibroblasts with only rare human PDGFRA positive cells (arrowheads) and were replaced by mouse fibroblasts." (PMID 37669366, 2023). "Recently, TC have been reported to be directly involved in skin alterations of patients affected by scleroderma, and the presence of PDGFRα on TC may have an important role in the pathophysiology of several organs." (PMID 24151977, 2013). "On the contrary, PDGFRα and PDGFRβ were highly expressed in scleroderma skin." (PMID 22697462, 2012). "We found that PDGFR on spindle-like cells is highly phosphorylated in scleroderma skin, in sharp contrast to normal skin where PDGFR and phospho-PDGFR are virtually undetectable (mean ± SEM: 0.89 ± 0.02 and 0.93 ± 0.02 for phospho-PDGFRα/PDGFRα and phospho-PDGFRβ/PDGFRβ, respectively)." (PMID 22697462, 2012). "An agonistic anti-PDGFRα monoclonal antibody, but not the non-agonistic one, induced enhanced collagen deposition, increased fibroblast activation markers, and vascular alterations in the dermis of human skin equivalents, leading to scleroderma-like skin fibrosis." (PMID 35409263, 2022). "Expression of phosphorylated PDGFRα and PDGFRβ could not be detected in spindle-like cells in the dermis of normal skin; on the contrary, these receptors were highly expressed on spindle-like cells in scleroderma skin." (PMID 22697462, 2012).
spina bifida (4 papers, 2007 to 2022). A congenital neural tube defect in which vertebrae are not fully formed. "Two of these (H1/H2) were overrepresented in patients with sporadic spina bifida and were associated with increased PDGFRA transcriptional activity." (PMID 34204341, 2021).
systemic sclerosis (4 papers, 2013 to 2023). A chronic disorder, possibly autoimmune, marked by excessive production of collagen which results in hardening and thickening of body tissues. "Human PDGFRα is a target of the autoimmune response in systemic sclerosis." (PMID 35409263, 2022). "In the context of fibrotic disease, the gp38 marker has been reported to be expressed in CD34−gp38+CD90+ reticular cells in the skin of the patients with systemic sclerosis and in mouse skin wounds as well as a subset of ADAM12+gp38+PDGFRα+ in skin and muscle acute injury stromal cells." (PMID 31417912, 2019).
allergies (3 papers, 2023 to 2024). "In this study, we showed that clemastine, an over-the-counter drug used for alleviating allergies, suppresses the propagation of patient-derived BTICs bearing PDGFRA amplification (as a surrogate representing the PN GBMs), as well as those resembling CL or MES subtypes." (PMID 37760589, 2023). "Here, we demonstrate that clemastine, an over-the-counter drug for treating hay fever and allergy symptoms, effectively attenuated the stemness and suppressed the propagation of primary BTIC cultures bearing PDGFRA amplification." (PMID 37760589, 2023).
bladder tumors (3 papers, 2011 to 2021). "The expression of PDGFRA mRNA clearly discriminated bladder tumors (NMIBC and MIBC) from normal control tissues (p < 0.0001, FDR < 0.0001), with PDGFRA expression in NMIBC and MIBC being approximately 0.274-fold higher than that in controls." (PMID 26225770, 2015).
cardiac hypertrophy (3 papers, 2017 to 2025). "PDGF-C induced fibroblasts activation, cardiac fibrosis, hypertrophy, and dilated cardiomyopathy through up-regulation and activation of PDGFRα." (PMID 28570599, 2017).
Carney-Stratakis syndrome (3 papers, 2015 to 2020). Carney-Stratakis syndrome is a recently described familial syndrome characterized by gastrointestinal stromal tumors (GIST) and paragangliomas, often at multiple sites. "However, nearly 10–15% of adult GIST and 85% of pediatric GIST are negative for KIT and PDGFRA mutations, as called wild-type (WT) GIST, which is a component of the Carney-Stratakis syndrome caused by the succinyl dehydrogenase (SDH)-mutations." (PMID 33238982, 2020).
Cerebral ischemia (3 papers, 2018 to 2025). Restriction of arterial blood supply to the brain associated with insufficient oxygenation to support the metabolic requirements of the tissue. "The interactions between tPA and LRP1 or PDGFRα during cerebral ischemia increase the expression of MMP2 and MMP9." (PMID 30186167, 2018). "During cerebral ischemia, neuronal depolarization can result in a surge of local and exogenous t-PA activity, which in turn leads to continued production of PDGF-CC, persistent activation of PDGFRα in the neurovascular unit, and, ultimately, loss of BBB integrity." (PMID 29850586, 2018).
colorectal adenocarcinoma (3 papers, 2012 to 2020). The most common type of colorectal carcinoma. "This work aimed to explore the PDGFRα expression/mutational hot spot exon 18 status and its association with clinicopathological features and RAS status in colorectal adenocarcinoma in order to assess its potential role in prognosis and treatment prediction." (PMID 33213472, 2020). "The present study evaluated the incidence of VEGFR2, PDGFRα and PDGFRβ TK domain genetic variants in different CRC cell lines (T84, LOVO, LS174T, HT29, LS180, SW48, SW480, COLO205) and in tumor samples of 92 patients diagnosed of colorectal adenocarcinoma." (PMID 23146028, 2012).
COVID-19 (3 papers, 2022 to 2023). A disease caused by infection with severe acute respiratory syndrome coronavirus 2. "Additionally, the expression of genes associated with endothelial dysfunction—namely CCL2, PDGFRA, PDGFB, and PDGFC—was also found to be increased in ACE2-positive brain cells of COVID-19 patients." (PMID 37239234, 2023). "The upregulation of PDGFRA and its ligands in COVID-19 suggests that this pathway could be a key therapeutic target for both COVID-19 and GBM." (PMID 37239234, 2023). "In addition, platelet-derived growth factor C (PDGFC) and receptor alpha (PDGFRA) were found to be more abundant in the COVID-19 group, with PDGFRA displaying such a trend only in the survivor subgroup." (PMID 35842415, 2022). "Further, the expression of genes involved in endothelial dysfunction, namely CCL2, PDGFRA, PDGFB, and PDGFC, is found to be increased in ACE2-positive brain cells of COVID-19 patients." (PMID 37239234, 2023).
cystitis (3 papers, 2022). Inflammation of the urinary bladder. "We hypothesized that loss-of-function in PDGFRα+ cells or SK channels could lead to DO in cystitis." (PMID 35332235, 2022). "Future studies concerning signaling mechanisms of PDGFRα + interstitial cells and their contribution to cystitis should examine downstream kinase targets including mTOR." (PMID 35528149, 2022). "Additionally, PDGFRα + interstitial cell signaling may be mediated by both pERK and pAKT pathways in cystitis." (PMID 35528149, 2022). "We investigated the effects of PDGFRα blockade with imatinib in mice with intermediate (48 h) and chronic (8 day) CYP-induced cystitis using prevention (i.e., imatinib via oral gavage before CYP treatment) and treatment (i.e., CYP treatment followed by intrabladder infusion of imatinib) methods." (PMID 35645740, 2022).
diffuse astrocytoma (3 papers, 2009 to 2020). A low-grade (WHO grade II) astrocytic neoplasm. "A statistically significant association between PDGFRA amplification and overexpression was found only in diffuse astrocytomas (grade II)." (PMID 19707201, 2009). "In addition, a statistically significant association (P=0.038) was found between PDGFRA amplification and overexpression in grade II diffuse astrocytomas." (PMID 19707201, 2009). "Attempts to molecularly define the aggressive type of diffuse astrocytomas have suggested several genetic markers such as RB1 pathway alterations (e.g., CDKN2A/B homozygous deletion or CDK4 amplification), PIK3R1 mutation, PDGFRA amplification, or G-CIMP low type in the methylation cluster." (PMID 33228806, 2020).
epilepsy (3 papers, 2017 to 2019). A brain disorder characterized by episodes of abnormally increased neuronal discharge resulting in transient episodes of sensory or motor neurological dysfunction, or psychic dysfunction. "In our epilepsy cases, missing early OPCs (PDGFRa+), activation of later OPCs (NG2+), and an overall lower content within mature oligodendroglia, led us to the conclusion that there is a cell breakdown (or burnout) because of insufficient maturation that prevents adequate myelination." (PMID 27750396, 2017).
essential thrombocythemia (3 papers, 2021 to 2022). A chronic myeloproliferative neoplasm that involves primarily the megakaryocytic lineage. "No rearrangement of PDGFRA, PDGFRB, FGFR1, or PCM1-JAK2; the Philadelphia chromosome; or BCR-ABL1 gene fusion should be detected as any diagnostic criteria for polycythemia vera (PV), essential thrombocythemia (ET), and primary myelofibrosis (PMF)." (PMID 34684141, 2021).
fatty liver disease (3 papers, 2017 to 2020). A reversible condition wherein large vacuoles of triglyceride fat accumulate in liver cells via the process of steatosis. "The Pdgfrα-Cre Ahrfl/fl knockout mice were also protected from increased adiposity, enlargement of adipocyte size, and liver steatosis while on the HFD compared to control mice." (PMID 32730300, 2020). "In addition, we found that PDGFRα expressed in the LD, WAT, heart, spleen and kidney of the pig, but could hardly be detected in the liver, which may be a reason why obese pigs resist fatty liver disease." (PMID 29140299, 2017).
fibrosis (3 papers, 2014 to 2024). the formation of excess fibrous connective tissue in an organ or tissue in a reparative or reactive process. "The co-localization of PDGFC- PDGFRA interaction with fibrotic areas and markers was notably more pronounced in slides obtained from MASH patients with fibrosis stage 3 and 4 scores, compared to healthy samples or those with fibrosis stage 1 and 2 scores." (PMID 38768139, 2024).
gastric adenocarcinoma (3 papers, 2019 to 2020). "Especially, the PDGFRA gene has been associated with tumor progression in stomach adenocarcinomas and has been associated with a poor prognosis." (PMID 31310640, 2019). "This together with the absence of c-KIT and PDGFRα mutations in the adenocarcinomas confirm that the major molecular pathways of tumor development are different in gastric adenocarcinomas and adjacent MGs." (PMID 33335133, 2020).
Hyperglycemia (3 papers, 2015 to 2021). An increased concentration of glucose in the blood. "The present study has investigated the effects of hyperglycemia on the expression of nNOS in differentiated PDGFRα-positive cells." (PMID 33805311, 2021). "Further experimentations revealed that hyperglycemia produced a significant increase in expression of nNOS in PDGFRα-positive cells." (PMID 33805311, 2021). "NO supported the survival of PDGFRα-positive cells under normoglycemic conditions, however nNOS expression increased significantly in response to hyperglycemia." (PMID 33805311, 2021). "This strongly supports the hypothesis that in normal conditions, NO supports the survival of the PDGFRα-positive cells; however, stressful events such as hyperglycemia can modulate the involvement of NO in cellular processes of the PDGFRα-positive cells." (PMID 33805311, 2021). "After the differentiation process was completed, PDGFRα-positive cells were used in further experimentations to conduct functional studies to investigate the effects of NO on the survival rate of these cells and the impact of hyperglycemia in nNOS expression in PDGFRα-positive cells." (PMID 33805311, 2021).
inflammatory bowel disease (3 papers, 2022 to 2024). A spectrum of small and large bowel inflammatory diseases of unknown etiology. "Here, the authors decipher subset-specific human stromal responses in inflammatory bowel disease and suggest that intestinal PDGFRA+CD142−/low fibroblasts guide monocyte transition to macrophages in human gut through GM-CSF." (PMID 38409190, 2024). "Additional pathologies where PDGFRα has been implied include inflammatory bowel disease, where PDGFRα-positive mesenchymal niche cells perturb epithelial proliferation and maturation." (PMID 38980580, 2024).
invasive ductal breast carcinoma (3 papers, 2005 to 2022). The most common type of invasive breast carcinoma, accounting for approximately 70% of breast carcinomas. "Similarly, in invasive ductal carcinoma, overexpression of PDGFRα correlates with metastasis." (PMID 36614038, 2022).
lymphedema (3 papers, 2022 to 2023). Excess fluid collection in tissues, causing swelling. "Although we observed expansion of the PDGFRA+ compartment in lymphedema, as previously suggested, there was significant patient-patient variability, with some clusters exhibiting patient-specific changes." (PMID 38131378, 2023). "Taken together, these findings suggest that the adipocyte stromal cell compartment is heterogeneous and composed of distinct adipogenic and fibrogenic cells, with expansion of PDGFRA-expressing cells in lymphedema." (PMID 38131378, 2023). "In this study, our results showed strong correlations between the expression of tryptase and PDGF-A and PDGFRα in adipose fibrosis of secondary lymphedema patients." (PMID 37886950, 2023). "Fourth, questions remain regarding the source of PDGFRα+ cells present in the lymphedema site; it remains unclear whether these cells are derived from local mesenchymal cells or from cells that traffic to the injury site." (PMID 38131378, 2023). "Single-cell RNA-Seq data obtained from human tissues and flow cytometric and histological evaluation of mouse tissues demonstrated increased presence of PDGFRα+ cells in lymphedema; human tissue analysis verified these cells have the capacity for adipogenic and fibrogenic differentiation." (PMID 38131378, 2023). "Our findings with the human lymphedema samples and the previous literature supported our decision to examine how rosiglitazone may impact PDGFRα+ cells." (PMID 38131378, 2023).
Lynch syndrome (3 papers, 2024 to 2025). An autosomal dominant hereditary neoplastic syndrome characterized by the development of colorectal carcinoma and a high risk of developing endometrial carcinoma, gastric carcinoma, ovarian carcinoma, renal pelvis carcinoma, and small intestinal carcinoma. "Importantly, our PDX model of CMMRD showed exactly the same methylation classification of the primary tumor: dpHGG, Rtk1 subtype, subclass A. This specific subtype is enriched in Lynch syndrome or CMMRD‐associated HGG, and approximately 33% of cases harbor PDGFRA amplification, like our case." (PMID 40880425, 2025).
myelodysplastic syndrome (3 papers, 2018 to 2025). A clonal hematopoietic disorder characterized by dysplasia and ineffective hematopoiesis in one or more of the hematopoietic cell lines. "Myeloproliferative neoplasms (MPNs) are a major subgroup of chronic myeloid neoplasms, alongside myelodysplastic syndromes (MDS), MDS/MPN overlap syndromes, and myeloid/lymphoid neoplasms, with eosinophilia associated with recurrent PDGFRA, PDGFRB, FGFR1, or PCM1-JAK2 rearrangements." (PMID 40650198, 2025).
myxofibrosarcoma (3 papers, 2019 to 2024). A malignant fibroblastic neoplasm arising from the soft tissue. "In fact, PDGFRA::USP8 gene fusion was previously reported from a primary cardiac myxofibrosarcoma in a 5 year old boy." (PMID 38401149, 2024).
myxoid glioneuronal tumor (3 papers, 2021 to 2024). A central nervous system benign neoplasm that is characterized by a dinucleotide mutation at codon 385 of the PDGFR gene. "This myxoid glioneuronal tumor, PDGFRA p.K385L-mutant, arose in the midbrain tectum rather than in the septum pellucidum, as in the previously-reported cases." (PMID 34297434, 2021).
neuroendocrine tumors (3 papers, 2021 to 2026). "The transcriptomic landscape of 24,887 single cells was obtained and characterized as 10 cellular clusters, including epithelial, neuroendocrine tumor cells, T&NK cells, B cells, RGS5+ fibroblasts, POSTN+ fibroblasts, PDGFRA+ fibroblasts, endothelial, myeloid cells, and mast cells." (PMID 34185421, 2021).
oral cancer (3 papers, 2020 to 2024). "For example, high levels of PDGFRA have been associated with regional metastasis and decreased survival in oral carcinoma." (PMID 35406617, 2022).
orofacial cleft (3 papers, 2017 to 2019). A disorder of facial skeleton that is characterized by cleft lip and/or cleft palate that result in feeding, speech and hearing problems caused by failures during development. "Several regions mapped to genes that have previously been implicated in the development of orofacial clefts (for example, TBX1, COL11A2, HOXA2, PDGFRA), and over 250 associations were novel." (PMID 28603561, 2017).
osteoporosis (3 papers, 2022 to 2025). A condition of reduced bone mass, with decreased cortical thickness and a decrease in the number and size of the trabeculae of cancellous bone (but normal chemical composition), resulting in increased fracture incidence. "Since osteoporosis is a clinical feature in many advanced FOP patients, bone mass and architecture in the lumbar vertebrae (L4) of AAV-treated Acvr1(R206H)Fl;PDGFRα-cre mice were assessed by microCT and histology." (PMID 36258013, 2022). "The absence of PDGFRA/B in osteoblasts leads to a reduction in osteoclast numbers and an increase in trabecular bone volume, underscoring its therapeutic potential for osteoporosis." (PMID 40130165, 2025).
rectal tumors (3 papers, 2016 to 2024). "The rectal tumors in this study harbored KIT exon 11 mutations, while both analyzed colonic cases were wild-type for KIT/PDGFRA/RAS." (PMID 39199677, 2024). "Moreover, high expression levels of PAI1 are associated with increased metastasis and invasion of rectal tumors in this cohort and TCGA database, respectively, which is correlated with EMT-associated and drug target genes expression, including PDGFRa, PDGFRb, FYN, PIM1 and BRAF." (PMID 32344898, 2020).